RHOB (ras homolog family member B)
Diseases named in the same sentence as RHOB in open-access papers (continued):
Sharing a sentence is not in itself a finding about the gene and the disease.
cancer (continued). "MiR-21 promotes the development of CRC by targeting directly RHOB, thus promoting the cancer cells proliferation, invasion, and inhibiting the programmed cell death." (PMID 34199293, 2021). "An example of the well-described retrogene in the cancer literature is RHOB exhibiting suppression activity." (PMID 33478113, 2021). "RhoB also contributes to cancer progression by regulating cell cycle progression, apoptosis, DNA damage responses, invasion, and migration." (PMID 34456862, 2021). "This network is the only one that involves RHOB- a cancer cell apoptosis modulator and, currently a research target as a cancer therapeutic." (PMID 34359782, 2021). "Several members of the Rho family of GTPases have been in the context of cancer angiogenesis, migration, and invasion, most notably RhoA, RhoB, RhoC, RhoG, Rac1, and Cdc42." (PMID 32089990, 2020). "Conversely to RHOA and RHOC, RHOB has been described to be downregulated in several malignancies where its expression promotes apoptosis in cancer cell lines and inhibits invasion." (PMID 31888022, 2019). "Moving beyond the use of RhoB as a prognostic biomarker, several studies have investigated the therapeutic usage of restoring RhoB levels in treating cancer." (PMID 31200451, 2019). "Enhancement of p300 binding during NSC126188 anti-cancer treatment favors induction of RHOB-mediated apoptosis in stomach carcinoma cells." (PMID 31200451, 2019). "Ras has been shown to upregulate the PI3K/Akt pathway leading to increased cell survival in several cancer types, while RhoB conversely decreases Akt mediated survival." (PMID 31200451, 2019). "As such, the PI3K/AKT pathway becomes a major modality by which RHOB, or lack thereof, mediates cancer invasiveness." (PMID 31200451, 2019). "RhoB appears to play a tissue-specific role in tumorigenesis, as such, uncovering and appreciating the potential for restoration of RHOB expression as a mechanism for cancer prevention or therapeutics serves as a practical application." (PMID 31200451, 2019). "RhoB, however, is the least studied amongst its immediate family members, especially in the context of tumorigenesis and cancer progression." (PMID 29385717, 2018). "Because of the several unique post-translational modifications that are distinct from RhoA and RhoC, RhoB is argued to be the most diverse protein of the Rho subgroup, a factor possibly contributing to its dualistic role in cancer." (PMID 29385717, 2018). "The substantial roles that RhoB seems to play in vascular and endothelial cells presumably gives rise to involvement in cancer vasculature with implications in angiogenesis." (PMID 29385717, 2018). "The following is a review of several studies which highlight the role of RhoB as an oncogene in different cancer types." (PMID 29385717, 2018). "Subsequent studies began to reveal emerging evidence for a cancer suppressive role for RhoB through inhibitory effects on cell proliferation, survival, invasion and metastasis." (PMID 29385717, 2018). "Many of these studies were performed years ago and any new signs of evidence involving RhoB in the FTI anti-cancer response has remained unresolved." (PMID 29385717, 2018). "In carcinomas in situ and in well-differentiated head and neck tumors, RhoB expression is quite prevalent." (PMID 29385717, 2018). "In cancer cells, geranylgeranylation of RhoB induces apoptosis and is required for RhoB degradation, while farnesylation of RhoB is associated with pro-proliferative effects." (PMID 28395021, 2017). "For example, RHOB is a mainly endosomal small GTPase that regulates actin organization and vesicle trafficking, which resulting in the suppression of cancer cell proliferation, survival, invasion, and metastasis." (PMID 28146424, 2017). "RhoB responds to farnesyl transferase inhibitor (FTI)-treatment by a gain-of-function mechanism that is characterized by elevation of the RhoB-GG form that inhibits proliferation or apoptosis of cancer cells." (PMID 25548921, 2014).
cancer (continued). "In contrast, RhoB has antiproliferative and proapoptotic effects in cancer cells, and overexpression of RhoB can inhibit cell migration, invasion, and metastasis." (PMID 25548921, 2014). "We provide evidence that ligand-bound TRβ activates the RhoB signaling pathway and inhibits cancer cell proliferation both in vitro and in vivo." (PMID 25548921, 2014). "RhoA, RhoB and Cdc42 play a crucial role in the development of cancer, being main factors responsible for cellular motility and loss of adhesion." (PMID 23420497, 2013). "Obviously, the expression of RhoB was obviously reduced or lost in the majority of malignant tumors." (PMID 24223801, 2013). "It is clear that RhoB expression is detected in normal ovary epithelium, borderline tumors, and decreases significantly in malignant tumors (P<05)." (PMID 24223801, 2013). "Most of what we know about the role of Rho GTPases in cancer cell invasion comes from the studies of the prototypic members RhoA, RhoB and RhoC, Rac1 and Cdc42." (PMID 22860091, 2012). "Here, we investigate the function of RhoB in regulating cell morphology and migration in cancer cells." (PMID 22724071, 2012). "Lastly, RHOB has been shown to be upregulated and negatively affect cell proliferation of some types of cancer cells." (PMID 23209612, 2012). "Some previous studies have revealed that RhoA and RhoC expression are frequently increased in human cancers, while RhoB is often down-regulated." (PMID 22860091, 2012). "Although a number of studies indicate growth stimulatory roles for RhoA and RhoC in cancer, the exact role of RhoB in tumorigenesis is still being defined." (PMID 21373644, 2011). "It has previously been shown that RhoB is necessary for mediating cell death in various cancer cells, and we have shown that it is similarly required for IR-induced cell death in MCF-7 cells." (PMID 21373644, 2011). "These studiessuggested that RhoB was detected in normal tissue yet itsexpression was dramatically lost during cancer progression in lung and head and necksquamous cell carcinoma." (PMID 21079744, 2010). "Proteins whose inhibition can mediate anti-cancer effects of FTIs include RhoB and the centromeric proteins CENP-E and CENP-F; most likely a combinatorial effect on many farnesylated proteins is necessary for the cytostatic and cytotoxic effects of FTIs." (PMID 18489761, 2008). "In parallel, other studies demonstrated that RhoB stimulates cell motility and migration or may even promote cancer metastasis." (PMID 38355625, 2024). "In addition, genes reported to be involved in immunological response to pathogens, such as IL-8, IFITM1, IFITM2, and RHOB were also significantly differentially expressed in cancer tissue." (PMID 38505585, 2024). "Decreased expression of RHOB has been reported in many cancer studies." (PMID 33478113, 2021). "RhoB can also regulate the membrane mobility of BTN3A1 on cancer cells." (PMID 34149914, 2021). "Thus, its overexpression promotes metastatic phenotype of cancers by targeting RHOB and suppressing its activity." (PMID 34199293, 2021). "RHOB is an important oncosuppressor, and a decrease in its expression promotes cancer." (PMID 33478113, 2021). "Due to RhoB promoting apoptosis in various cancer cells, this finding illustrates that in some cancers, Smurf1 might act as an oncoprotein to degrade RhoB and facilitate tumorigenesis." (PMID 33718111, 2020). "Similarly, AGS cells and melanoma cells treated with protocatechuic acid exhibited activation of RHOB and downregulation of the Ras/Akt/NF-kB pathway, which led to a decrease in matrix metalloproteinase-2 activity in cancer cells." (PMID 31200451, 2019).
cancer (continued). "As such, plant-based diets containing gallic acid and protocatechuic acid may be useful in preventing cancer through a variety of mechanisms, including the activation of RHOB." (PMID 31200451, 2019). "Thus, LMF performs a significant role in antitumor effect by upregulating RhoB expression in several cancer types." (PMID 31331053, 2019). "In addition to their fundamental functions, Rho GTPases such as RhoA and RhoB play a significant role in cancer progression and inflammation." (PMID 31331053, 2019). "Additionally, EGFR was found to inhibit RHOB promoter activity in cancer cells derived from pancreatic (Panc-1) tumors, cervical (C33A) tumors, and lung (A549) tumors." (PMID 31200451, 2019). "Delarue and colleagues examined cancer cells from various origins, including human breast, colon, lung, pancreatic, and brain tumors, with farnesyltransferase and geranylgeranyltransferase I inhibitors in an effort to restore RHOB expression." (PMID 31200451, 2019). "Farnesylated RhoB promotes growth responses in cancer cells and we investigated whether inhibition of protein farnesylation will have a protective effect." (PMID 28395021, 2017). "In addition, we found that besides DNA‐damaging drugs, PTX, an antimicrotubule drug used to treat cancers, also increased the expression and activation of RhoB." (PMID 26915688, 2016). "In conclusion, Sp1 driven up-regulation of miR-19a promotes cancer by targeting RHOB." (PMID 26041879, 2015). "RhoB responds to FTI-treatment by a gain-of-function mechanism that is characterized by elevation of the geranyl-geranylated isoform of RhoB that inhibits the proliferation of cancer cells." (PMID 25548921, 2014). "This feature of drug-resistant cells might be gainfully exploited in cancer gene therapy of drug-resistant tumors with down-regulated RhoB expression." (PMID 24466204, 2014). "RhoB, a member of small GTPases belonging to the Ras protein superfamily, might have a suppressive activity in cancer progression." (PMID 24223801, 2013). "We hypothesize that RhoB normally regulates cancer cell migration by increasing the stability of integrin-mediated adhesions and integrin activity, thereby promoting lamellipodial protrusion and migratory polarity." (PMID 22724071, 2012). "Furthermore, suppression of RhoB is a critical step leading to transformation in a variety of cancers, including those of the lung and cervix." (PMID 19317917, 2009). "RhoB levels have been shown to decrease as cancer progresses." (PMID 19317917, 2009). "However, RHOB has been shown to play a role in the development of other cancers." (PMID 39944833, 2025). "However, RhoB attracts growing interest, as its expression is altered in several cancer types." (PMID 38355625, 2024). "Therefore, RHOB restoration might benefit cancer prevention and healthspan by antagonizing RAS/PI3K/AKT/mTOR and facilitating Myc turnover." (PMID 31200451, 2019). "Thus, a reduction in RhoB mRNA from aged mice might increase the occurrence of cancer in a tissue specific manner, as was explained in a human NSCLC line." (PMID 31200451, 2019). "There are 3 Rho isoforms but little evidence of Rho isoform-specific effectors, so the mechanisms by which the isoforms exert differential effects are unknown, but RhoA and C tend to exhibit oncogenic effects in a number of cancers whereas RhoB suppresses tumourigenesis." (PMID 27487152, 2016). "However, whether RhoB is involved in the GC roles in tissue and systemic adaptation to hypoxia and protecting cancer cells against chemotherapy is largely unknown." (PMID 26915688, 2016). "Thus, altered expression and activity of RhoB may be crucial for cancer progression and therapeutic responses." (PMID 25548921, 2014). "Similarly, RhoB (2.16-fold increase) is a well-characterized small GTPase that can inhibit cell proliferation, survival and invasion, and it is often down-regulated in cancer cells." (PMID 24161199, 2013).
cancer (continued). "The antagonistic role of RHOB and ABCA7 in cancer reveals that there are complex interactions among Hub-EGFR.Sig, which was also confirmed in our subsequent miRNA–mRNA and TF-mRNA interactive network analysis." (PMID 40574864, 2025). "According to the findings, in both RhoB knockout cell lines, 5-FU and OXL exhibited potent anti-cancer activity, with 5-FU being the best candidate among the two drugs." (PMID 38355625, 2024). "All cancer lines tested, including SW480, SW480-KO13 (RhoB knockout), SW480-KO55 (RhoB knockout), HCT116 and HCT116-OE (RhoB overexpressed), exhibited cytotoxicity to 5-FU and OXL." (PMID 38355625, 2024). "Additionally, in contrast to RHOA and RHOC, RHOB localizes not only at the plasma membrane but also on endosomes, multivesicular bodies, and in the nucleus, which could contribute to its contrasting behaviors in cancer biology." (PMID 34771549, 2021). "We will focus in particular on five members of the RHO GTPase family, including RHOA, RHOB, RHOC, RAC1, and CDC42, to illustrate the role of lncRNAs in cancer progression." (PMID 34771549, 2021). "LATS2, MCC, DCC, RHOB, TRIM13, LIMD1, and GPC3 also strongly and positively regulated gene down-expression in cancer." (PMID 33580150, 2021). "Out of these, RHOB, VDR, and PTGS2 were the only candidates with FDA-approved anti-cancer drugs, with one each for RHOB and VDR, and 20 for PTGS2." (PMID 30842898, 2019). "In these networks, PTGS2, VDR, RHOB, PIM1, HSPA1L, HSPA1A, and SPHK1 were used as targets for cancer drug development, previously." (PMID 30842898, 2019). "Soon after, the Prendergast group demonstrated that the overexpression of a geranylgeranylated form of RhoB, was required for the FTI-mediated apoptotic response of Ras-transformed cancer cells." (PMID 29385717, 2018). "RhoB, RhoC and ROCK-1 mRNA levels were significantly higher in ccRCC tissues compared with non-cancer tissues." (PMID 21119662, 2011). "Trastuzumab was shown to modify cancer cell functions and biology through the regulation of several molecular targets, such as PTEN, MEK1-2 and RhoB." (PMID 20588279, 2010). "Our results point to the down-regulation of RhoB as a potential marker for late-stage MDS, similar to its diminished expression in other late-stage cancers." (PMID 19768111, 2009). "In addition, we observed significant downregulation of genes that mediate cell adhesion and EMT, including RHOB, shown to be required for neural crest delamination in the trunk, and EPCAM, which has been shown to participate in cancer cell EMT." (PMID 33613313, 2021). "It has been well-documented that angiogenesis is a major contributing factor to cancer progression, so it is not surprising that several studies look at endothelial response to changes in expression or activation of RhoB." (PMID 29385717, 2018). "For example, although these three Rho members similarly interact with Rho effectors thus far identified, RhoA, RhoB, and RhoC act on different effectors, namely ROCKi/2, integrins and formin FMNL3, respectively, and exert different functions in cancer cell migration and morphogenesis." (PMID 29749605, 2018). "Out of 57 cases of malignant tumors, RhoB negative expression was detected in 27 cases, and only faint staining was observed in 14 cases." (PMID 24223801, 2013). "As a Rho protein, RhoB cycles between GTP and GDP bound states, forming interactions with a variety of effectors that modulate activity and influence important processes in cancer." (PMID 23339407, 2013). "This is not surprising considering that RhoB is in many cases growth-inhibiting and has been shown to be down-regulated in cancer cells." (PMID 17653061, 2007). "We found lots of them might play a key role in the transformation of enterocyte progenitor cells to cancer cells such as MALAT1, B2M, EEF1A1, RPL5, B3GNT7, RHOB and ACTB might play a key role in the transformation of enterocyte progenitor cells to cancer cells." (PMID 36944972, 2023).
cancer (continued). "RhoB appears to function as a suppressor or negative modifier in cancer progression." (PMID 31200451, 2019). "Interestingly we found that the intrinsic radiosensitivity of carcinoma cells was not modulated by paracrine factors secreted either by Wt or RhoB-/- fibroblasts." (PMID 25635683, 2015). "Important cancer related genes identified for this phenotype are CDK6 gene, which inhibits proliferation of human mammary epithelial cells; SIAT4C, which is down-regulated in RCC, RHOB, which is known to be a pro-apoptotic and tumor suppressor gene, and the FLT1 and TFF3 gene." (PMID 19458770, 2007).
infection (9 papers, 2013 to 2025). The state of being infected such as from the introduction of a foreign agent such as serum, vaccine, antigenic substance or organism. "Endogenous RhoB was markedly increased at 2 h post infection (hpi) in a MOI (multiplicity of infection)-dependent manner." (PMID 33972537, 2021). "UPEC infections increase RhoB, Beclin 1 and LC3 levels in bladder epithelium in vivo, whereas Beclin 1 and LC3 levels as well as UPEC clearance are substantially reduced in RhoB+/− and RhoB−/− mice upon infection." (PMID 33972537, 2021). "To explore the role of RhoB during UTIs, we first assessed the protein level of RhoB in human bladder epithelial cell line 5637 upon infection with the UPEC strain CFT073." (PMID 33972537, 2021). "In addition, RhoB overexpression enhances infection of viruses pseudotyped with either Ebola or vesicular stomatitis viral glycoprotein." (PMID 34834920, 2021). "We were unable to detect RhoB gene and protein levels at the 3 hr timepoint, suggesting that future work may need to assess expression of this factor earlier during infection." (PMID 34350128, 2021). "However, in contrast to the caveolin-1 results in the infection condition, LD4-PP increased the expression of RhoB both on the mRNA and protein level in E. coli-infected cells." (PMID 41415272, 2025). "RCAN1, SLC6A6, RHOB, DUSP, TGM3, and TP53INP2 DEGs, which are related to DNA damage-induced apoptosis, autophagy, the cell cycle, and inflammatory repression, were also upregulated after vPdR-36U infection." (PMID 40006915, 2025). "We found three genes that were commonly activated with infection with SCV2 at both 12 and 24 hpi (DUSP1, HES1, KLF2) and some non-congruent genes at 12 hpi (CCL5, ZBP1, NRXN2, STAB1, SLC25A47, CXCL11) and 24 hpi (FOXA2, RHOB)." (PMID 37504520, 2023). "Although not significant, there was a trend toward increased RhoB at the mRNA level basally in miR-21−/− macrophages and also following infection with L. monocytogenes." (PMID 28589100, 2017). "In contrast to these observations, under similar conditions for infection of SK-BR-3 or MDA-MB-231 cells, the adenoviral RhoB vector either slightly decreased or had no significant biological effect on cell proliferation." (PMID 23339407, 2013).
neurodegenerative disease (2 papers, 2022 to 2025). A disorder of the central nervous system characterized by gradual and progressive loss of neural tissue and neurologic function. "LEF1-associated target genes related to neurodegenerative diseases, such as EGR1, RHOB, and ID2, exhibit binding peaks." (PMID 40918098, 2025).
adenocarcinoma (1 paper, 2019). A common cancer characterized by the presence of malignant glandular cells. "By utilizing IHC and RT-qPCR to compare RhoB in control patients and patients with known advanced lepidic adenocarcinoma, they found that patients with more aggressive forms of lepidic adenocarcinoma had greater losses of RHOB expression." (PMID 31200451, 2019).
bacterial infections (1 paper, 2021). "Here, using a uropathogenic Escherichia coli (UPEC) infection model, we demonstrate that bacterial infection upregulates RhoB, which subsequently promotes intracellular bacteria clearance by inducing LC3 lipidation and autophagosome formation." (PMID 33972537, 2021).
genetic disease (1 paper, 2009). "RhoB is found in MVB and is strongly accumulated in this compartment when the MVB lipids are selectively altered either by pharmacological means, such as U18666A and endocytosed anti-LPBA antibodies, or by genetic disease." (PMID 19956591, 2009).